CRP (C-reactive protein)
Diseases named in the same sentence as CRP in open-access papers (continued):
Sharing a sentence is not in itself a finding about the gene and the disease.
sarcopenia (continued). "Association between CRP level and sarcopenia using 2-piecewise regression models." (PMID 39969369, 2024). "Furthermore, to bolster our findings with more robust evidence, we employed Mendelian randomization (MR) analysis, utilizing genetic variations in CRP as the exposure variable, to investigate the prospective causal association between CRP and sarcopenia." (PMID 39502753, 2024). "The presence of sarcopenia associated significantly with albumin, haemoglobin and CRP." (PMID 37906352, 2023). "Therefore, an additional RF plot was built without splitting the two samples to get a selection of variables most associated with sarcopenia, and found that albumin, CRP, and folate ranked high." (PMID 37110223, 2023). "Interestingly, recent research has shown that preoperative sarcopenia and elevated systemic inflammatory markers, such as the modified Glasgow Prognostic Score including both CRP and albumin levels, were associated with a decreased survival." (PMID 37371699, 2023). "Accumulated epidemiological, clinical, and basic research evidence indicates that inflammatory markers and the hormonal pathway (e.g., interleukin-6, C-reactive protein, myokine, and serum testosterone) are involved in the association between sarcopenia and cognitive impairment." (PMID 37139093, 2023). "However, sarcopenia was associated with a lower level of prealbumin (p = 0.01) and higher levels of alpha-1 acid glycoprotein (p = 0.03) and CRP (p = 0.02)." (PMID 37058153, 2023). "The ROC analysis of cfDNA, CRP, IL-1β and bilirubin ranged from 0.6 to 0.7, which confirms the association between sarcopenia and inflammatory mediators and indicates high clinical usefulness of cfDNA and bilirubin in sarcopenia prediction." (PMID 37465171, 2023). "In a meta-analysis, sarcopenia was associated only with high CRP level." (PMID 35575465, 2022). "A similar study observed an association between sarcopenia with CRP, ESR, and adiponectin." (PMID 36291982, 2022). "All these assumptions could explain why, in the multivariate analysis, the association between AGEs and sarcopenia lost its strength when compared to BMI and CRP." (PMID 35884793, 2022). "Besides, the association between DII and sarcopenia also remains consistent and stronger in subjects with high levels of CRP and NLR." (PMID 35634405, 2022). "The present study showed a significant association between the determination of sarcopenia status (i.e., muscle mass index, gait speed, and handgrip strength) and CRP levels, which were associated with low gait speed, low muscle mass (only in female older adults), and high hs-CRP." (PMID 35570546, 2022). "Logistic regression analysis was carried out to associate the inflammatory markers IL-6, TNF-α, and CRP with sarcopenia, and it was found that TNF-α was the only significant predictor of sarcopenia in tertile 3 or at levels > 71.2 [(OR = 5.85), 95% (1.07–32.08)]." (PMID 36291982, 2022). "After adjusting for the significant variables from the univariate logistic regression analysis and relevant clinical confounders, high CRP at enrollment (OR 3.18, 95% CI 1.06–9.54) and low BMI at onset (OR 0.60, 95% CI 0.48–0.75) remained significantly associated with sarcopenia in SSc patients." (PMID 36307496, 2022). "Age, gender, BMI, and history of cerebrovascular diseases were significantly associated with both sarcopenia and severe sarcopenia, while serum uric acid as well as CRP level were significantly associated with severe sarcopenia (OR, 0.715; 95% CI, 0.524–0.977; p = 0.035)." (PMID 35198574, 2022). "In our research, the presence of sarcopenia (HR 2.08, 95% CI 1.15-3.76) and high CRP level (HR 2.57, 95% CI 1.42-4.66) were associated with the worst PFS (median 7.7 months), whereas the absence of these two factors was associated with the best PFS (median 27.9 months)." (PMID 35575465, 2022). "CRP has been found to be associated with sarcopenia in both men and women." (PMID 34943268, 2021).
sarcopenia (continued). "Finally, sarcopenia is associated with inflammation demonstrated by increased serum C-reactive protein (CRP) levels, interleukin-6 (IL-6), and TNFα." (PMID 35010928, 2021). "According to the results, sarcopenia may be associated with elevated blood CRP levels; further studies are needed to clarify the link." (PMID 34943268, 2021). "Indeed, compelling evidence indicates that increased levels of circulating C-reactive protein (CRP) and proinflammatory cytokines are associated with lower muscle mass and strength and increased risk of sarcopenia in older adults." (PMID 34917235, 2021). "Subjects with altered CRP, sarcopenia and severe anxiety appear more at risk of severe fatigue." (PMID 34315951, 2021). "A recent prospective study confirmed this hypothesis, suggesting an association of chemotherapy-induced sarcopenia with serum C-reactive protein, IL-8, and TNF-alpha levels." (PMID 33809587, 2021). "After multivariate regression, including all significant risk factors in univariate analysis, only abnormal CRP values (OR 5.1, 95% CI 1.3–20.2), severe anxiety (OR 3.7 95% CI 0.93–15) and sarcopenia (OR 4.4, 95% CI 1.1–20.1) were identified as risk factors for severe fatigue in IBD patients." (PMID 34315951, 2021). "In our study population, RFM was a negative confounder between CRP and sarcopenia, because it was positively associated with CRP and inversely associated with sarcopenia, suggesting that the direction of ORs of CRP can be flipped if multivariable models do not adjust for RFM." (PMID 34836213, 2021). "In addition, a routine clinical inflammation biomarker such as C-reactive protein (CRP) has recently been shown to be positively associated with sarcopenia and sarcopenic obesity." (PMID 32075166, 2020). "Particularly, sarcopenia has been associated with increased serum CRP levels." (PMID 33318308, 2020). "In addition, other studies found an association between elevated CRP and sarcopenia or identified higher levels of CRP as a risk factor for the loss of muscle strength." (PMID 30784011, 2019). "Lower adiponectin:leptin ratios and elevated levels of CRP, cortisol and IL-8 were associated with increased risk of sarcopenia as defined by the EWGSOP algorithm at follow-up, although the strength of associations varied according to the other covariates included in the models." (PMID 29101476, 2018). "Log CRP was positively associated with the prevalence of sarcopenia (models 7, 8a, 9a, 8b, and 9b)." (PMID 29447254, 2018). "In addition, according to a recent meta-analysis, sarcopenia is associated with higher serum inflammatory parameters, particularly increased CRP levels." (PMID 30134867, 2018). "At multivariate analysis, only age ≥60 years and the presence of a disability were associated with an increased risk of sarcopenia (OR = 3.3; CI 1.4–7.7, p = 0.005; OR = 3.0; 95% CI 1.2–7.9, p = 0.01, respectively), while a higher CRP value almost reached statistical significance (p = 0.07)." (PMID 30513782, 2018). "The impacts of clinicopathologic features, including age, sex, histologic type, albumin, C-reactive protein, body mass index, pretreatment sarcopenia, weight loss rate, skeletal muscle change, and pathologic stage, on OS were evaluated using multivariable analysis." (PMID 28861809, 2017). "Additionally, a study focusing on patients with inflammatory bowel diseases found that sarcopenia, severe anxiety, and elevated C-reactive protein levels were significantly associated with severe fatigue, further emphasizing the complex interplay between physical and psychological health factors." (PMID 40373026, 2025). "Since dietary intake of anti-inflammatory nutrients, including n-3 fatty acids, vitamin C, and dietary fibers, was shown to be associated with reduced CRP level and reduced risk of low muscle strength, dietary intervention targeting hsCRP may be effective against possible sarcopenia." (PMID 40871726, 2025).
sarcopenia (continued). "Additionally, higher serum CRP concentrations have been linked to sarcopenia and frailty." (PMID 40422566, 2025). "Therefore, more longitudinal studies need to be performed to determine whether our observed correlation between CRP level and sarcopenia is causal." (PMID 39969369, 2024). "Finally, although we found that RCT patients with sarcopenia had significantly higher levels of CRP and ESR, the underlying pathophysiological mechanisms driving this relationship remain unclear." (PMID 39033299, 2024). "However, the association between CRP level and sarcopenia needs to be further investigated." (PMID 39969369, 2024). "However, the association between CRP levels and sarcopenia among the general adult population in the USA is unknown." (PMID 39969369, 2024). "This study focused on assessing whether CRP levels were associated with sarcopenia." (PMID 39969369, 2024). "Additionally, we found chronic inflammation caused by inflammatory cytokines (e.g., CRP) might be one of the contributing factors for sarcopenia and related comorbidities." (PMID 33661964, 2021). "Neutrophil/lymphocyte ratio (NLR), tumor necrosis factor alpha (TNF-α), interleukin 6 (IL-6), C-reactive protein (CRP) are the markers most frequently associated with sarcopenic status and they could be considered as risk factors for the development of sarcopenia itself." (PMID 34944975, 2021). "CRP levels negatively correlated with the rate of skeletal muscle protein synthesis, which may support the idea that low-grade inflammation is implicated in sarcopenia development in frail people." (PMID 31613904, 2019). "To date, TNF-α, IL-6, albumin and CRP have shown a relation with the development of low muscle strength or muscle mass over time, however, the current body of evidence fails to reveal a marker of chronic inflammation that is univocally associated with measures of sarcopenia in older people." (PMID 31455238, 2019). "Given that inflammatory pathways, as well as oxidative stress, are well documented drivers of sarcopenia (the age-related loss of muscle mass and strength), one may have expected a greater degree of association between indices of CRP recovery and rate of improvement in physical function." (PMID 27467771, 2016). "Increased CRP and TNF-α levels are associated with sarcopenia in older adults, suggesting a role of systemic inflammation in its pathogenesis." (PMID 42267078, 2026). "This study confirmed the significant association between elevated inflammatory markers (including TNF‐α and CRP), and sarcopenia among patients with CKD." (PMID 41457350, 2026). "Elevated amounts of pro-inflammatory cytokines like interleukin-6 (IL-6) and tumor necrosis factor-α (TNF-α), as well as C-reactive protein (CRP), are linked to sarcopenia." (PMID 40649397, 2025). "It is also known that a chronic inflammatory milieu (high IL-6, TNF-α, interleukin-1 (IL-1), and C-reactive protein “CRP”) is correlated with sarcopenia in aging." (PMID 41348866, 2025). "Growing evidence shows that serum levels of tumor necrosis factor (TNF)-α, interleukin (IL)-6, and C-reactive protein (CRP) are elevated in individuals with sarcopenia, typically reaching levels 2–4 times higher than those observed in younger controls." (PMID 40678078, 2025). "Among the laboratory values, urea and CRP levels were statistically considerably higher in the sarcopenia group." (PMID 41393007, 2025). "These patients, while nutritionally compromised per GNRI, exhibited lower inflammatory markers (CRP, ferritin), less severe vascular calcification, and better survival outcomes compared to the sarcopenia and MSS groups." (PMID 41323996, 2025). "Classification-CRP is significantly elevated in SO, with WBC serving as a specific marker, while the selective association of TNF-α with sarcopenia suggests the existence of subtype-specific pathways driving chronic inflammation." (PMID 40507924, 2025).
sarcopenia (continued). "Our study integrates high-sensitivity C-reactive protein (Hs-CRP) measurements with sarcopenia assessment, offering a more comprehensive evaluation of the inflammatory and metabolic factors associated with POCD." (PMID 41331912, 2025). "Inflammatory markers such as C-reactive protein (CRP) and interleukin-6 (IL-6) are frequently elevated in individuals with inflammatory sarcopenia and are strongly associated with progressive declines in muscle mass and function." (PMID 40277851, 2025). "These markers are strongly linked to age-related morbidity and mortality: elevated CRP predicts CVD onset in older adults, and TNF-α/IL-6 correlate with sarcopenia and disability." (PMID 41561801, 2025). "Previous research on patients with RA has suggested that high CRP concentrations are related to sarcopenia and low muscle mass." (PMID 40019564, 2025). "Data from two studies involving 191 SSc patients were analyzed to explore the relationship between sarcopenia and C-reactive protein (CRP) levels." (PMID 40095540, 2025). "Diet-related inflammation and markers like C-reactive protein (CRP) and systemic immune-inflammatory index (SII) are also linked to sarcopenia, highlighting inflammation’s central role in its development." (PMID 40625358, 2025). "Concurrently, the application of ML methods to clinical data identified significant markers of sarcopenia, including albumin, C-reactive protein (CRP), folate, and vitamin D." (PMID 41303670, 2025). "This process is marked by the upregulation of inflammatory biomarkers such as C-reactive protein (CRP), IL-6, and TNF-α, all of which are associated with the development of sarcopenia." (PMID 39940321, 2025). "This study aimed to examine the association of biomarkers recommended by the ESCEO guidelines—including adiponectin, myostatin, P3NP, CRP and TNF‐α—with sarcopenia diagnostic criteria using plasma‐derived EV markers in a prospective cohort." (PMID 40162588, 2025). "The cross-sectional nature of the study hinders the ability to establish a causal link between Hs-CRP/HDL-C and sarcopenia, necessitating future prospective research with expanded sample sizes." (PMID 40672942, 2025). "Analysis of inflammatory profiles revealed significantly elevated CRP levels in SO, with WBC as a specific marker, while TNF-α was associated with sarcopenia, suggesting a subtype-specific role of chronic inflammation." (PMID 40507924, 2025). "We demonstrated for the first time that nutritional frailty, expressed by high E-DII, was closely related to high CRP/albumin ratio in sarcopenia and probable sarcopenia." (PMID 41345186, 2025). "The available reports on changes in concentrations of CRP, IL-1β, IL-6 and TNFα confirmed that inflammation was a critical component of sarcopenia progression." (PMID 41345186, 2025). "Differences in inflammatory characteristics between sarcopenia and SO were also detected, which mainly consist of a greater increase in C-reactive protein (CRP), in SO." (PMID 41226798, 2025). "In several cross-sectional studies, patients with sarcopenia demonstrated a higher erythrocyte sedimentation rate and CRP level than healthy controls." (PMID 41345186, 2025). "Albumin concentration was significantly lower in subjects with sarcopenia (p = 0.002), while CRP levels were significantly higher (p = 0.035), but still within the clinical reference ranges that do not indicate an acute inflammatory process (>5 mmol/L)." (PMID 40430249, 2025). "RF models determined the most important variables related to sarcopenia: albumin, C-reactive protein (CRP), vitamin D and folates." (PMID 40362666, 2025). "The strong link between inflammation and dialysis-related sarcopenia has been repeatedly reported, with C-reactive protein among the inflammatory markers emerging as the most common predictor of sarcopenia in these patients." (PMID 40142260, 2025).
sarcopenia (continued). "This study validated that the mGNRI, which incorporates inflammation (as indicated by CRP levels) and nutritional reserves (body weight relative to ideal body weight), exhibits high sensitivity (> 80%) for identifying sarcopenia in hospitalized older patients." (PMID 41262732, 2025). "Participants with sarcopenia, especially those with inflammation, had lower BMI and significantly higher CRP and IL-6 levels, highlighting the role of chronic inflammation in muscle deterioration." (PMID 40277851, 2025). "Nevertheless, further studies are still needed to explain epidemiological and clinical significance of CRP/albumin ratio in predictions of sarcopenia and the survival of old elderly adults in conjunction with the nutritional status." (PMID 41345186, 2025). "Multivariate logistic regression models, adjusted for demographic and clinical covariates, were employed to assess the association between the Hs-CRP/HDL-C ratio and sarcopenia." (PMID 40672942, 2025). "Previous studies have reported that individuals with sarcopenia tend to have higher C-reactive protein (CRP) levels and a higher NLR compared to the general population." (PMID 40075586, 2025). "Patients with sarcopenia were found to exhibit elevated CRP concentrations and greater mobility issues." (PMID 40422566, 2025). "The area under the curve (AUC) value, which is 0.81 (95% CI: 0.749−0.871), indicates the accuracy of the CRP test in diagnosing sarcopenia." (PMID 39502753, 2024). "The adjusted OR of sarcopenia of 1.86 (95% CI, 1.37–2.51; P < .001) was determined by 2 piecewise regression models for those having the CRP level of 1.8." (PMID 39969369, 2024). "The relationship between the MAFLD and sarcopenia were mediated by C-reactive protein (mediation proportion: 15.9%) and high-density lipoprotein cholesterol (mediation proportion: 18.9%)." (PMID 38491346, 2024). "Numerous clinical and epidemiological studies have shown that various plasma inflammatory markers, including CRP, high-sensitivity C-reactive protein, and interleukin-6, are often elevated in patients with sarcopenia and correlate with their prognosis." (PMID 38638440, 2024). "The findings also suggest the need to improve and treat elevated CRP levels and reduced BMR to prevent cognitive decline and accelerated aging, as well as the development of sarcopenia risk." (PMID 39764251, 2024). "Previous studies have indicated that these inflammatory biomarkers inversely correlate with muscle strength and that C-reactive protein levels inversely correlate with sarcopenia." (PMID 38613070, 2024). "It has also been reported that older people with sarcopenia show significantly higher levels of circulating IL-6 and TNF-α and that high levels of IL-6 and CRP increase the risk of loss of muscle strength." (PMID 39203857, 2024). "Elevated levels of IL-6, IL-1β, TNF-α, and C-reactive protein (CRP) have been implicated in the loss of muscle mass and strength in sarcopenia." (PMID 39101140, 2024). "It was found that patients with sarcopenia have increased pro-inflammatory cytokine levels (interleukin-6, tumor necrosis factor α (TNFα)), C-reactive protein, and decreased levels of anti-inflammatory cytokine interleukin-10." (PMID 38505257, 2024). "A meta-analysis of 17 studies, encompassing 11,249 participants, found that individuals with sarcopenia had significantly higher levels of CRP compared to controls." (PMID 38638440, 2024). "Based on subgroup analysis, CRP levels were related to sarcopenia in males (OR, 1.03; 95% CI, 1–1.05) and individuals aged <50 years (OR, 1.03; 95% CI, 1.01–1.05), drinking (OR, 1.02; 95% CI, 1–1.03), and body mass index ≥ 25 kg/m2 (OR, 1.02; 95% CI, 1–1.03)." (PMID 39969369, 2024). "It is crucial to acknowledge the significance of using glucosamine, regulating CRP levels, and improving and resolving the drop in BMR to address the gradual aging of the population, including cognitive loss and the development of sarcopenia." (PMID 39764251, 2024).